NUMB (NUMB endocytic adaptor protein)
Diseases named in the same sentence as NUMB in open-access papers (continued):
Sharing a sentence is not in itself a finding about the gene and the disease.
tumor (continued). "Increased NUMB exon 9 inclusion (by AON) in A549 cells promoted early primary tumor growth compared to controls, whereas tumors with increased Ex9sk expression exhibited slower growth." (PMID 39863103, 2025). "Both pharmacological and genetic strategies validate that targeted‐blocking the MUC1–PP2A axis significantly elevates PKCζ activity and phosphorylation of NUMB, ultimately suppressing CSLCs and tumor growth in vitro and in vivo." (PMID 40349179, 2025). "In these BC models, CRL7FBXW8/proteasome inhibition is sufficient to rescue NUMB expression, inhibit tumor growth, and revert the defects in the SC compartment, ultimately leading to a reduction in the number of tumor‐initiating cells (TICs)." (PMID 40411418, 2025). "Specifically, patients with NUMB 3 had a markedly higher hazard of death, greater odds of recurrence, larger tumor size, and higher tumor grade compared to those with lower NUMB expression (NUMB 1)." (PMID 40296944, 2025). "Combined inhibition of the MUC1–PP2A axis using LB100/GO203 with etoposide restores PKCζ activity and enhances NUMB phosphorylation, effectively suppressing CSLCs proliferation and tumor growth." (PMID 40349179, 2025). "Aside from its link to clinical outcomes, NUMB expression was also correlated with tumor size, a pathological parameter." (PMID 40296944, 2025). "We classified BCs with an IHC score of ≥2.0 (as observed in the normal mammary gland) in at least 70% of tumor cells as NUMB proficient, while the remainders were labeled as NUMB‐deficient." (PMID 40411418, 2025). "During development, NUMB is a determinant in the asymmetric division of stem cells to maintain tissue homeostasis; in the cancer cell, it acts mostly as a tumor suppressor in reducing self-renewal capacity and stemness thus limiting tumor growth." (PMID 39463384, 2024). "VGF expression was opposite to NUMB expression in this tumor cohort, which is compatible with our previous observation (Middle)." (PMID 38528565, 2024). "The opposition in VGF and NUMB expression was also noticed in 18/20 tumor types in the TCGA dataset." (PMID 38528565, 2024). "Concurrent knockdown of NUMB largely restored the tumor formation, albeit with a 7- to 10-day delay compared to control cells." (PMID 39463384, 2024). "Quercetin decreases tumor growth by inhibiting the activation of NUMB and Hedgehog signaling pathway, suggesting that NUMB has potential as a biomarker for cancer." (PMID 39092224, 2024). "Though a known tumor suppressor, NUMB has context-dependent roles in specific cancers highlighting the complexity of its functions and emphasizing the importance of a clear understanding of the signaling circuitry." (PMID 39463384, 2024). "Using the GEPIA, the correlations between the mRNA levels of NUMB/NUMBL with patients individual tumor stages of different cancers from TCGA were compared." (PMID 37657045, 2023). "In tumors, overexpression of miR-335 has been linked to increased tumor growth and decreased expression of RBM10, as well as increased expression of long NUMB isoforms (p72/71)." (PMID 36672267, 2023). "The new NUMB functions in RPECs uncovered here are consistent with NUMB’s role as a tumor suppressor in a variety of malignancies." (PMID 37566749, 2023). "In order to explore the association between protein phosphorylation and oncogenicity, the differences in NUMB/NUMBL phosphorylation levels between primary tumor tissues and normal tissues were compared." (PMID 37657045, 2023). "Whereas the relevance between NUMB mRNA expression and pathological stages only presents in 5 tumor species." (PMID 37657045, 2023). "Together, we concluded that NUMB p71/p72 and p65/p66 isoforms displayed opposing influence on tumor migration and metastasis in vivo." (PMID 35457181, 2022).
tumor (continued). "And miR-146a-5p also induces tumor formation by inhibiting NUMB protein, resulting in the asymmetric segregation of CRC stem cells." (PMID 36237545, 2022). "NUMB also suppresses tumor progression, including the regulatory effects on the processes of physiological development." (PMID 35478938, 2022). "Accordingly, NUMB is involved in a broad spectrum of cellular phenotypes in homeostasis and in cancer where it mainly function as a tumor suppressor." (PMID 36346211, 2022). "Some abnormally regulated genes in our prognostic signature participated in tumour initiation and development, including NUMB, RSRC2, TMC6, CASP8, TRIO, and COMMD5." (PMID 34772375, 2021). "The Cargo protein MAP17 interacts with NUMB to overexpress the Notch pathway, leading to CSCs feature activation of tumor cells." (PMID 34374886, 2021). "In particular, tumor suppressor lncRNAs such as lncRNA PAUPAR or NUMB can be used as therapeutic molecules to reduce tumor progression in UM." (PMID 34439196, 2021). "miR-9-5P inhibition or NUMB overexpression can attenuate many biological properties of PCSCs, leading to prominent inhibition of clonogenic and sphere-forming activities, tumor growth and metastasis." (PMID 34045601, 2021). "Because NOTCH and NUMB have evolved similar functions in cell fate determination and tumor angiogenesis, this biological pathway is a possible target for anticancer treatments." (PMID 34587981, 2021). "The fixed nature of the PIAS4 and NUMB lesions supports a model suggesting that these likely promoted the BRCA2 phenotype of this tumor." (PMID 34011996, 2021). "Recently, study showed that NUMB phosphorylation plays a crucial role in tumor-initiating cell self-renewal and liver tumorigenesis via the Nanog pathway." (PMID 33117795, 2020). "This phosphorylation site has been shown to be a key activator of AKT28, suggesting a possible involvement of NUMB in tumor progression." (PMID 30890698, 2019). "In other words, the p66 isoform of NUMB is anti-proliferative and can potentially function as a tumor suppressor." (PMID 30726988, 2019). "Genes such as CFLAR, EP300, GBP2, HEYL, KLF7, NOTCH1 or POFUT showed a similar correlation with NUMB or NUMBL in the three tumor types considered." (PMID 29507685, 2018). "Next, we determined the genes that correlated to NUMB or NUMBL in all considered tumor types and then compared the individual tumor types to obtain a map of common genes correlating to NUMB or NUMBL expression in various tumors." (PMID 29507685, 2018). "Further, inhibition of NUMB phosphorylation successfully inhibited Tumor development in a mouse model." (PMID 29460395, 2018). "MAP17 overexpression activates the Notch pathway due to the direct interaction between MAP17 and NUMB in tumor cells." (PMID 29650022, 2018). "A comparison of each tumor type allowed us to identify a small number of genes that were equally related to NUMB and NUMBL, different genes related to similar functions, and genes with differential expression." (PMID 29507685, 2018). "Because this interaction is mediated by the last 13 amino acids of MAP17, deletion of this region (tMAP17, truncated MAP17) blocked the interaction of MAP17 with NUMB and resulted in a loss of MAP17-induced tumor-promoting properties." (PMID 29650022, 2018). "We have recently showed that NUMBL behaves, such as NUMB, its close relative, as a tumor suppressor gene regulating the Notch pathway." (PMID 29507685, 2018).
tumor (continued). "We showed that only that the downregulation of only NUMB or NUMBL causes an increment in the tumorigenic properties of cells, allowing us to focus on their roles as tumor suppressor genes." (PMID 29507685, 2018). "The activation of key factors of NOTCH signaling pathway was correlated to stem-like cells harboring and long term tumor recurrence, and rescued NUMB by miR-129 inhibited NICD." (PMID 29262559, 2017). "We found that there is a strong correlation between the presence of NUMB in disease networks and the degree of invasiveness of the corresponding tumor determined by growth in other regions of the brain." (PMID 27354287, 2016). "The remaining three tumor lines having NUMB in their disease networks were minimally or non-invasive." (PMID 27354287, 2016). "Because increased NUMB was correlated with reduced tumor invasiveness, it can be considered as a prognostic target not as a therapeutic target." (PMID 27354287, 2016). "Mounting evidence points to a role for the cell-fate determinant NUMB as a tumor suppressor in distinct types of human cancers." (PMID 23771628, 2014). "In broader terms, it has also been reported that low NUMB mRNA expression array of various cell lines from tumor types treated with AKT/PI3K inhibitors correlates with resistance to PI3K/mTOR inhibition." (PMID 23300998, 2013). "Additionally, Spearman's correlation analysis demonstrated a positive correlation between NUMB expression and tumor grade (rho = 0.361, p = 0.020)." (PMID 40296944, 2025). "Multiple studies addressing NUMB isoform functions support a general model in which increased expression of exon 9 included isoforms contribute to tumor growth and metastasis by antagonizing the tumor suppressive function of the exon 9 skipped NUMB isoforms." (PMID 39863103, 2025). "Significant NUMB expression (NUMB 3) was found to be correlated with more aggressive clinicopathological characteristics, including higher tumor grade (p = 0.039), larger tumor size (p = 0.016), and elevated recurrence rate (p = 0.033)." (PMID 40296944, 2025). "What is more, these data suggested that NUMB/NUMBL might play crucial roles in the tumor progression of different cancers from TCGA." (PMID 37657045, 2023). "Besides, using the GEPIA dataset, top 100 genes in all tumor expression data of TCGA that correlated with NUMB- or NUMBL were gathered respectively." (PMID 37657045, 2023). "Interestingly, there is controversy regarding the role of NUMB as a tumor suppressor, as oncogenic behavior has been observed in some cases." (PMID 36672267, 2023). "The evidence from this study implies that NUMB can have both tumor promoting and inhibiting capacities and those opposite impacts of NUMB might rely on tumor types." (PMID 37657045, 2023). "NUMB has been initially identified as a critical cell fate determinant that modulates cell differentiation via asymmetrical partitioning during mitosis, including tumor cells." (PMID 37657045, 2023). "In cancer, NUMB is a tumor suppressor that regulates, among others, Notch and Hedgehog signaling." (PMID 36346211, 2022). "We reasoned that NUMB might mediate isoform-specific effects through the distinct regulation of Notch1 activity in tumor cells." (PMID 35457181, 2022).
tumor (continued). "A recent study also found that HMGA1 downregulates NUMB in brain tumor stem cells, which could maintain the tumor cells in a more de-differentiated, stem-like state and contribute to tumor progression." (PMID 34572547, 2021). "LncRNA NUMB acts as a tumor suppressor by inhibiting cell proliferation and invasion." (PMID 34439196, 2021). "This treatment significantly reduced tumor size and volume compared to the vehicle treatment, as assessed by ultrasound sonography and micro-CT imaging; thus, this demonstrated the in vivo efficacy of the aPKCζ inhibitor in the context of NUMB activity." (PMID 32555153, 2020). "It has also been shown to play a role in the pathogenesis of certain cancers, although it remains controversial whether NUMB functions as an oncoprotein or tumor suppressor." (PMID 30726988, 2019). "We have found that NUMB and NUMBL exhibit mutual exclusivity in human tumors, suggesting that the associated tumor suppressor role is regulated by only one of the two proteins in a specific cell, avoiding duplicate signaling and simplifying the regulatory network." (PMID 29507685, 2018). "Thus, although both NUMB and NUMBL are considered tumor suppressors, an increment in the expression of at least NUMB cannot be assumed to lead to an increase in a tumor suppressor gene due to the observed alternative splicing." (PMID 29507685, 2018). "A possible explanation for the different effects on different pathways, correlating genes to either an oncogene or a tumor suppressor, may be plausible if we consider recent results correlating the alternative splicing of NUMB in tumors." (PMID 29507685, 2018). "The network approach also predicted that NUMB was present in a subpopulation of the tumor lines." (PMID 27354287, 2016). "Furthermore, evaluation of NUMB mRNA expression in different tumor histological grades showed that its expression was higher in grade 1 and lower in grade 3 tumors (n = 1411, p < 0.00001) (upper right)." (PMID 27506933, 2016). "In addition to its role in the regulation of these physiological developmental processes, NUMB has been shown to be a tumor suppressor in cancer progression." (PMID 27506933, 2016). "We revealed that the network approach could identify a biomarker of a clinical feature by showing that the presence of NUMB relates to tumor invasiveness." (PMID 27354287, 2016). "However, another key target of mir146a is represented by NUMB that has been shown to regulate cell fate and growth, acting as tumor suppressor." (PMID 25986346, 2015). "This shift in the division modality, which is supported by the increase in the asymmetric distribution of NUMB, might be of practical clinical relevance because asymmetric division plays a tumour-suppressive role." (PMID 24833610, 2014). "For example, paracrine effects have been shown to play a role in tumor progression, which has not been linked to NUMB signaling pathway." (PMID 24980814, 2014). "NUMB is an evolutionarily conserved protein that is broadly expressed in mammalian tissues, and recent findings suggest that NUMB may exert tumor suppressor effects across various tumor types." (PMID 40710326, 2025). "Thus alterations in NUMB exon 9 splicing are a common event across multiple tumor types." (PMID 39863103, 2025). "Interestingly, low NUMB expression results in enhanced BRCA1-dependent tumor formation." (PMID 34374886, 2021). "However, when we compared the genes that were correlated to NUMB or NUMBL in each individual tumor type, we found common positively or negatively correlated genes, suggesting that NUMB and NUMBL participate in different gene regulatory processes, depending on the tissue." (PMID 29507685, 2018). "We next tested whether NUMB could also inhibit tumor metastasis in vivo." (PMID 27506933, 2016). "The restoration of NUMB following in vivo BTZ treatment was confirmed by IB and IHC analyses of the tumor outgrowths at the end of the experiment." (PMID 40411418, 2025).
tumor (continued). "Immunohistochemical analyses revealed increased levels of TBC1D15, NUMB, NOTCH1, and TOM20 in the tumor tissues of NSG mice injected with CD133(+) TICs." (PMID 38409448, 2024). "Expression of NICD, the nuclear fragment of NOTCH1 that is shown to be downstream of NUMB but also feeds back to NUMB, completely reversed the effect of RAB4A knockdown on the tumor forming ability." (PMID 39463384, 2024). "Here, we sought to validate, in a xenograft mouse model, the essential role of NUMB, NOTCH1, and SOX2 in RAB4A-driven tumor formation." (PMID 39463384, 2024). "Knockdown of NUMB, or overexpression of NICD (the active fragment NOTCH1) or SOX2, rescued the in vitro sphere-forming and in vivo tumor-forming abilities that were lost upon RAB4A knockdown." (PMID 39463384, 2024). "Then the links between NUMB/NUMBL and tumor pathogenesis were further explored, containing differential gene expression, pathological features, prognostic survival, genetic mutation, protein phosphorylation, and relative cellular pathway." (PMID 37657045, 2023). "Unexpectedly, the analysis of expression level of NUMBL between tumor and normal tissues shows that dysregulation of NUMBL emerges in 27 of 33 tumor types of TCGA data library, more extensive than NUMB." (PMID 37657045, 2023). "Overexpression of the NUMB gene (NUMB endocytic adaptor protein) in CD44-positive cancer stem cells inhibited invasiveness and clonal formation capabilities leading to tumor growth and metastasis inhibition." (PMID 37461792, 2023). "NUMB, VCL, MAP3K7 and EXOC1 exon skipping events are examples of known splicing events that can be also observed in tumor tissue." (PMID 36304260, 2022). "In other tumor entities, MSI proteins have been shown to bind the NOTCH inhibitor NUMB, thus increasing notch activity." (PMID 34768932, 2021). "To address the role of NUMB in CD44+ PCSCs, we altered the expression of NUMB in the CD44+ and CD44− PC3 cells and then performed tumor invasion, clone formation and sphere formation assays." (PMID 34045601, 2021). "NUMB and NUMBL are commonly described as proteins with a very similar function, characterized as tumor suppressors." (PMID 29507685, 2018). "Here, we showed that NUMB and NUMBL presented mutual exclusivity in tumors, suggesting that the tumor suppressor effect on the Notch pathway is regulated by one protein at a time, thus simplifying the regulatory network." (PMID 29507685, 2018). "NUMB and NUMBL have been considered tumor suppressor genes with very similar functions because both can regulate the Notch pathway." (PMID 29507685, 2018). "Additionally, SCSES was the only method to uncover that NUMB exon 12 was more frequently included in three solid tumor cell lines (HCC1954, HCT116 and HepG2) than the blood tumor cells (HL-60), in agreement with recent studies." (PMID 41145486, 2025). "Levels of miR-9-5p are elevated in CD44+ prostate cancer stem cells (PCSCs) and exhibit a negative correlation with the expression of NUMB, a tumor suppressor in PCSCs." (PMID 40710326, 2025). "Phosphorylation of NUMB revealed significant differences between tumor and normal patients, especially S438 locus exhibited aberrant phosphorylation levels in 4 types of tumors (LUAD, KIRC, COAD, and UCEC) among all primary tumor tissues." (PMID 37657045, 2023).